POGLUT2 (protein O-glucosyltransferase 2)
Description:
Protein glucosyltransferase that catalyzes the transfer of glucose from UDP-glucose to a serine residue within the consensus sequence peptide C-X-N-T-X-G-S-F-X-C. Can also catalyze the transfer of xylose from UDP-xylose but less efficiently. Specifically targets extracellular EGF repeats of proteins such as NOTCH1, NOTCH3, FBN1, FBN2 and LTBP1. May regulate the transport of NOTCH1 and NOTCH3 to the plasma membrane and thereby the Notch signaling pathway.
Synonyms: ERp58; EP58; KDELC1; MGC5302; KDEL1
Tractability: Antibody: UniProt predicts a signal peptide or a membrane-spanning region. PROTAC: ubiquitination databases record sites on it.
Gene: Protein-coding gene on chromosome 13 (102,784,281 to 102,799,040, reverse strand). Ensembl gene ENSG00000134901.
Subcellular location: Endoplasmic reticulum lumen
Subcellular location (Human Protein Atlas): Nucleoplasm
Gene Ontology:
Molecular function: EGF-domain serine glucosyltransferase activity; EGF-domain serine xylosyltransferase activity; UDP-glucosyltransferase activity; UDP-xylosyltransferase activity; glucosyltransferase activity
Biological process: protein O-linked glycosylation via glucose
Cellular component: nucleoplasm; endomembrane system; endoplasmic reticulum lumen
Genetic constraint (gnomAD): Loss-of-function variants: 31 observed, 36.92 expected, observed/expected ratio (o/e) 0.84, 90% interval 0.63 to 1.13. The upper end of that interval is the gene's LOEUF score, 1.13, which puts it in group 4 of 6, group 1 being the genes least tolerant of losing a copy. Missense variants: 423 observed, 465.43 expected, observed/expected ratio (o/e) 0.91, 90% interval 0.84 to 0.99. Synonymous variants: 153 observed, 172.73 expected, observed/expected ratio (o/e) 0.89, 90% interval 0.78 to 1.01.
Homologues: Orthologues: chimpanzee POGLUT2 (99% identical), macaque POGLUT2 (97% identical), dog POGLUT2 (95% identical), pig POGLUT2 (94% identical), guinea pig POGLUT2 (93% identical), mouse Poglut2 (92% identical), rabbit POGLUT2 (91% identical), rat Poglut2 (91% identical), tropical clawed frog poglut2 (72% identical), zebrafish poglut2 (65% identical). Paralogues in human: POGLUT3 (52% identical), POGLUT1 (23% identical).
Diseases named in the same sentence as POGLUT2 in open-access papers:
POGLUT2 is named in the same sentence as 12 diseases in open-access papers, as found by Europe PMC text mining. Sharing a sentence is not in itself a finding about the gene and the disease. The quoted sentences say what the papers report.
clear cell renal cell carcinoma (2 papers, 2022). "POGLUT2 was an independent prognostic factor and was used to construct a prognostic signature in clear cell renal cell carcinoma, but few studies have examined the tumor mechanism." (PMID 35899200, 2022).
acute myelogenous leukemia (1 paper, 2022). "According to the previous studies about POGLUT1, a member from the same family of POGLUT2, elevated POGLUT1 expression was found in hematopoietic malignancies, including primary acute myelogenous leukemia and T-ALL." (PMID 36158688, 2022).
breast carcinoma (1 paper, 2022). "On immune checkpoint genes in breast cancers, POGLUT2 was positively correlated with CTLA4, CD274, TIGIT, LAG3, and PDCD1." (PMID 36158688, 2022). "To further test the possible molecular mechanisms, we performed Western blotting to check the effects of POGLUT2 knockdown in two breast cancer cell lines." (PMID 36158688, 2022). "Expression of POGLUT2 was determined in four breast cancer cell lines, including MDA-MB-468, MDA-MB-231, MCF-7, and BT474, and the highest gene and protein expression were respectively found in MCF-7 and MDA-MB-231 cells." (PMID 36158688, 2022). "The mechanisms of POGLUT2 in breast cancer were briefly evaluated via its connection with Notch signaling." (PMID 36158688, 2022). "Validated in breast cancer, the knockdown of POGLUT2 exerted a significant inhibitory effect on cell growth, apoptosis, and metastasis and suppressed tumor progression in rats by regulating Notch-related signaling." (PMID 36158688, 2022). "Meanwhile, immunohistochemistry analysis of POGLUT2 in breast cancer tissues revealed increased levels of POGLUT2 compared to control tissues." (PMID 36158688, 2022). "In specific breast cancer, POGLUT2 was positively correlated with StromalScore, ESTIMATEScore, and ImmuneScore and negatively correlated with Tumor purity." (PMID 36158688, 2022). "Furthermore, POGLUT2 knockdown of breast cancer cells was established, followed by in vitro biological function assays and in vivo tumor growth study." (PMID 36158688, 2022). "Finally, we explored the mechanisms of POGLUT2 in breast cancer via a brief evaluation of its connection with Notch signaling." (PMID 36158688, 2022). "Moreover, the univariate and multivariate Cox regression analyses demonstrated that POGLUT2 (p < 0.05) acted as an independent prognostic indicator of breast cancer together with age and stage (p < 0.001)." (PMID 36158688, 2022). "The results showed that POGLUT2 knockdown could delay the tumor growth and progression of breast cancer." (PMID 36158688, 2022). "Additionally, the enhanced effect of POGLUT2 on breast cancer development has been confirmed in the present study." (PMID 36158688, 2022). "Increased levels of POGLUT2 could result in the dysregulated immune cell infiltration and tumor microenvironment and showed a significant regulatory effect on the progression of breast cancer through Notch-related signaling." (PMID 36158688, 2022). "In specific breast cancer using the data from CIBERSORT, POGLUT2 was found positively correlated with monocyte, macrophage, and infiltration scores and negatively correlated with B cells, CD8 T cells, and conventional T cells." (PMID 36158688, 2022).
Marfan syndrome (1 paper, 2024). A disorder of the connective tissue. "The altered characteristics of the Poglut2/3 DKO smooth muscle cells are reminiscent of Marfan syndrome, where rounded smooth muscle cells in the aorta are attributed to elastic fiber fragmentation observed by TEM." (PMID 38844137, 2024).
cancer (6 papers, 2021 to 2025). A tumor composed of atypical neoplastic, often pleomorphic cells that invade other tissues. "The results indicated that POGLUT2 was positively correlated with cancer-associated fibroblasts, macrophages, monocytes, and neutrophils and negatively correlated with B cells, T cells, and NK cells in most of the cancers." (PMID 36158688, 2022). "Moreover, increased gene mutation and amplification, methylation, and CNA of POGLUT2 were found in several types of cancers." (PMID 36158688, 2022). "POGLUT2 was mainly expressed in stromal cells as verified by StromalScore, ESTIMATEScore, ImmuneScore, and Tumor purity, and POGLUT2 was positively correlated with cancer-associated fibroblasts, macrophages, monocytes, and neutrophils in the tumor microenvironment." (PMID 36158688, 2022). "Here, we found that POGLUT2 was mainly expressed in stromal cells, which is verified by StromalScore, ESTIMATEScore, ImmuneScore, and Tumor purity, and POGLUT2 was positively correlated with cancer-associated fibroblasts, macrophages, monocytes, and neutrophils in the tumor microenvironment." (PMID 36158688, 2022). "In the present study, we aimed to evaluate the role of POGLUT2 in pan-cancer through bioinformatics analysis and experimental verification." (PMID 36158688, 2022). "Our results showed that increased levels of POGLUT2 were found in multiple types of cancer tissues and cell lines." (PMID 36158688, 2022). "Due to the heterogeneity of gene expression and function, the specific role and mechanism of POGLUT2 need further investigations in various human cancers." (PMID 36158688, 2022). "Expression, gene mutation and amplification, methylation, and copy number alteration (CNA) of POGLUT2 were evaluated using The Cancer Genome Atlas (TCGA), Cancer Cell Line Encyclopedia (CCLE), and Genotype-Tissue Expression (GTEx) databases." (PMID 36158688, 2022). "Considering the critical role of gene mutation and amplification, methylation, and copy number alteration (CNA) in tumor development and progression, we also plotted figures that showed the ratio variation of POGLUT2 in different types of cancers." (PMID 36158688, 2022). "Moreover, the elevated mean expression of POGLUT2 was confirmed in tumor tissue and cancer cell lines." (PMID 36158688, 2022). "Moreover, the high- and low-expression grouping also confirmed that significantly increased survival in POGLUT2 low-expression patients in most types of cancers." (PMID 36158688, 2022). "Moreover, we also evaluated the role of POGLUT2 on survival and disease progression in pan-cancer based on TCGA data." (PMID 36158688, 2022). "In summary, our results here demonstrated that increased levels of POGLUT2 in cancer could result in dysregulated immune cell infiltration and tumor microenvironment." (PMID 36158688, 2022). "Increased levels of POGLUT2 were found in multiple types of cancer tissues and cell lines." (PMID 36158688, 2022). "Moreover, POGLUT2 on survival and disease progression in pan-cancer was performed using TCGA data." (PMID 36158688, 2022).
tumor (5 papers, 2021 to 2025). "In vivo results indicated that POGLUT2 knockdown decreased the tumor growth as verified by tumor size, tumor volume, and tumor weight." (PMID 36158688, 2022). "Firstly, a significant correlation could be found between POGLUT2 and StromalScore, ESTIMATEScore, ImmuneScore, and Tumor purity." (PMID 36158688, 2022). "In vitro and in vivo results showed that POGLUT2 knockdown could delay tumor growth and progression." (PMID 36158688, 2022). "Moreover, we also found that immune infiltration and tumor microenvironment evaluation using the ImmuneScore, ImmuCellAI, and TIMER databases and POGLUT2 correlated with drug resistance analysis using the GDSC2 database." (PMID 36158688, 2022). "In the results of pair tissue comparison, elevated POGLUT2 gene levels were found in most tumor tissue compared to normal tissue except in PRAD and KICH." (PMID 36158688, 2022).
POGLUT2 also shares sentences with these, for which no sentence is quoted: colon cancer (1 paper); Crohn disease (1); fibrosis (1); hepatic diseases (1); ovarian carcinoma (1); pancreatitis (1).